ERG (ETS transcription factor ERG)
Diseases named in the same sentence as ERG in open-access papers (continued):
Sharing a sentence is not in itself a finding about the gene and the disease.
periodontitis (1 paper, 2022). An acute or chronic inflammatory process that affects the tissues that surround and support the teeth. "We conclude that rs11084095 and rs4284742 are putatively causal for the genome-wide significant associations with periodontitis at SIGLEC5 that impair ERG and MAFB binding, respectively." (PMID 34852650, 2022).
pleuropulmonary blastoma (1 paper, 2025). A malignant neoplasm affecting the lungs and/or the pleura. "In this study, the identification of an EWSR1::ERG gene rearrangement in a case of pleuropulmonary blastoma—a finding not previously reported in this tumor type—underscores the evolving role of molecular profiling in refining diagnosis and understanding tumor biology." (PMID 40868080, 2025).
primary biliary cirrhosis (1 paper, 2017). "Finally, we show that ERG expression is lost in liver EC from cirrhotic patients with fibrosis related to alcoholic liver disease (ALD) or primary biliary cirrhosis (PBC) and inversely correlates with increased markers of EndMT." (PMID 29026072, 2017).
retinoblastoma (1 paper, 2024). A malignant tumor that originates in the nuclear layer of the retina. "Chemotherapeutic.Overexpression of ETS related gene (ERG) in prostate cells causes resistance to cabazitaxel.Tumors lacking retinoblastoma exhibit a more favourable response to cabazitaxel." (PMID 39351434, 2024).
rosacea (1 paper, 2021). A chronic erythematous skin disorder that affects the face. "Among the 264 upregulated genes were 12 overlapped TFs in rosacea lesions, including STAT1, FOXE1 and ERG." (PMID 34290700, 2021).
spindle cell neoplasm (1 paper, 2025). A benign or malignant neoplasm characterized by the presence of neoplastic spindle cells. "Immunohistochemistry confirmed the recurrent tumor as a spindle cell neoplasm, with immunopositivity for CD31 (80-90%), CD34 (>90%), ERG (5-10%), and STAT6 (>90%)." (PMID 40861561, 2025). "As previously stated, immunohistochemistry findings confirmed the recurrent tumor as a spindle cell neoplasm, with immunopositivity for CD31 (80-90%), CD34 (>90%), ERG (5-10%), and STAT6 (>90%)." (PMID 40861561, 2025).
Stillbirth (1 paper, 2021). Death of the fetus in utero after at least 22 weeks of gestation. "In livestock, the SNPs within or around the ERG gene were significantly associated with multiple traits (e.g., feet and leg conformation, stature, and stillbirth) in Holstein cattle." (PMID 34706644, 2021).
systemic sclerosis (1 paper, 2018). A chronic disorder, possibly autoimmune, marked by excessive production of collagen which results in hardening and thickening of body tissues. "In contrast to ERG, the function of FLI1 is less-characterized in ECs; its ablation results in upregulation of CTSL and CXCL6 and downregulation of CXCL5 and CCN1 in the context of systemic sclerosis." (PMID 30500808, 2018).
thoracic aortic aneurysm (1 paper, 2025). An aneurysm formed in the wall of the proximal portion of the descending aorta proceeding from the arch of the aorta. "In a single-cell transcriptome analysis of ascending thoracic aortic aneurysms, expression of ERG was found to be decreased in five cell clusters, when compared to healthy controls, suggesting a role of ERG in the maintenance of the aortic wall." (PMID 40630904, 2025).
thrombosis (1 paper, 2019). "In this study, we show that inducible chronic endothelial-specific deletion of ERG in adult mice leads to systemic coagulopathy with spontaneous thrombosis and/or hemorrhages in selected vascular beds." (PMID 31676784, 2019).
thyroid angiosarcomas (1 paper, 2024). "By immunohistochemistry, thyroid angiosarcomas are strongly and diffusely positive for pan-endothelial markers, i.e., CD31, CD34, FLI-1 and ERG, but lack expression of thyroid-related immunomarkers including thyroglobulin, TTF1 and PAX8." (PMID 39422760, 2024).
tumor (587 papers, 1994 to 2026). "Although correlative data suggest an association between ERG fusion and certain tumor phenotypes, the strengths of these associations vary widely." (PMID 40427518, 2025). "The ERG transcription factor (ETS-related gene) is implicated in various cancers, where it plays a key role in maintaining endothelial homeostasis and promoting tumor angiogenesis." (PMID 40862714, 2025). "In our cohort, ERG expression showed a significant association with advanced pathological stage (r = 0.315, p = 0.03), consistent with its role in tumor progression." (PMID 40863209, 2025). "Downregulating the expression of ERG in HPCs significantly reduces the number of PDGFRα+ CAFs and the infiltration of tumour-associated macrophages in HCC, thereby suppressing hepatocarcinogenesis." (PMID 39827226, 2025). "The TMPRSS2/ERG rearrangement can be associated with aggressive tumor features, with incidences varying from 15% to 72%." (PMID 40427154, 2025). "Having defined an ERG-specific chromatin context associated with tumor initiation, we postulated that the transcriptional programs activated by ERG likely involve one or more chromatin modifying enzymes." (PMID 40858905, 2025). "Logistic regression further supported the association between ERG positivity and advanced tumor stage (OR = 5.18, p < 0.05)." (PMID 40863209, 2025). "This lack of comprehensive molecular annotation has confounded efforts to parse the specific contribution of ERG to tumor aggressiveness, especially in the presence of the loss of PTEN or other concurrent mutations." (PMID 40427518, 2025). "Regarding clinicopathological characteristics and tumor focality, ERG overexpression showed a trend to be associated with a younger age in both MF and UF cases." (PMID 38017230, 2024). "In UF PCa, ETV1 overexpression was related to pT3 tumor stage (p = 0.031), and ERG overexpression was associated with perineural infiltration (p = 0.044), the latter also showing a trend to be related to younger patients (p = 0.058)." (PMID 38017230, 2024). "We provide evidence of a nonsense germline pathogenic variant in the RB1 gene and the presence of the EWRS1/ERG fusion gene in EWS tumor tissue in our patient." (PMID 39596402, 2024). "Association of the clinicopathological features with MVD by ERG expression in tumor and adjacent areas among patients with CRC." (PMID 38186453, 2023). "We found that miR-410 expression depends upon the tumor subtype, with those with ERG fusion, ETV1 fusion and SPOP mutations having a lower miR-410 expression as compared to other subtypes." (PMID 38201476, 2023). "Of note, tumor ERG expression and PTEN loss were both significantly associated with more extensive residual tumors in the RP specimen." (PMID 37109028, 2023). "Our group previously identified the presence of 2 immediately adjacent, but distinct, tumor foci found to have ERG rearrangement and F133V SPOP mutation." (PMID 35050902, 2022). "To investigate this further, we first analyzed the sub-structure of ERG+ and ERG− tumor cells separately to identify distinct underlying cell states." (PMID 35013146, 2022). "The availability of new research tools and model systems and the characterization of novel patient cohorts will help to further address ERG biology in PCa and other tumor types and to understand the differences between ERG physiological and pathogenic roles." (PMID 35267426, 2022). "As to the expression and predictive value of each ERG in the risk score formula, we first analyzed the gene expression level in tumor and in normal samples." (PMID 35095892, 2021). "Briefly we observed that relapsed tumors have an increase in KB content while tumor cells have reduced nuclear AR, increase of cytoplasmic AR and loss of ERG expression as compared with controls." (PMID 34584218, 2021).
tumor (continued). "While mutant SPOP renders tumor cells susceptible to androgen deprivation therapies, ERG promotes sensitivity to high-dose androgen therapy and pharmacological inhibition of wild type SPOP." (PMID 33531470, 2021). "Conversely, we show that the ERG oncogene’s presence increases the susceptibility of tumor cells to high-dose androgen therapy, while cells expressing mutant SPOP remain largely unaffected." (PMID 33531470, 2021). "Overall, our data indicates that the ERG-S96E phosphomimetic mutation abrogates the need for AKT activation in ERG-mediated tumor formation." (PMID 34314419, 2021). "Transmembrane protease, serine 2-erythroblast transformation-specific (TMPRSS2-ETS) genetic fusion, is a molecular subtype (ETS-related gene (ERG) positive) of PCa associated with cancer invasiveness found in 50% of PCa tumours." (PMID 34944438, 2021). "ERG-deleted tumour subclones were most likely to possess drivers mutations (35%; Qbinomal = 0.0016), whereas BCR-ABL1 positive tumour subclones contained the lowest frequency (4%; QBinomal = 0.052)." (PMID 34753926, 2021). "Depletion or inhibition of USP9X led to reduced ERG expression that was linked to impaired PCa signature gene expression and the inhibition of ERG-positive tumour growth in mouse xenograft models." (PMID 34066106, 2021). "Detecting TMPRSS2:ERG fusion in urine was found to be associated with PCa detection, mortality and with tumor volume, and high GS." (PMID 34503059, 2021). "Given the notion that wild type SPOP dampens AR function in the context of ERG to sustain tumor growth, we asked if VCaP cells are particularly susceptible to increased DHT levels." (PMID 33531470, 2021). "This was especially true of ERG-deleted tumours where 44% possessed a subclonal RAS/RTK variant (accounting for 89% of RAS/RTK mutations in the subtype) compared to 8% with a clonal variant." (PMID 34753926, 2021). "Evidence suggest higher frequencies of TMPRSS2-ERG gene fusion in PCa tumors of EA men compared to AA men; although ERG-negative status in AA men shows association with higher-grade tumor indices and a less favorable clinical outcome." (PMID 34820334, 2021). "Imputed SNPs rs34349373 and rs2055272, two intronic variants in TBC1D22B (TBC1 Domain Family Member 22B), a GTPase activating protein for Rab family, were significantly (< 10-6) associated with ERG positive phenotype in any tumor foci." (PMID 32341752, 2020). "The SNPs were associated with ERG fusion status either by index tumor or by any tumor foci positive for ERG." (PMID 32341752, 2020). "It integrates data on inherited susceptibility and tumor ERG status within a well-defined cohort of men with a median longitudinal follow-up of 7.5 years." (PMID 32341752, 2020). "The overexpression of SOX9 caused neoplasia and promoted invasion of tumor in prostate of murine models in the same way as ERG." (PMID 31027362, 2019). "The poathologic complete response or minimal residual disease rate was 30% in ELAP-treated patients and 16% in EL-treated patients; tumor ERG positivity, or PTEN loss, was associated with more extensive residual tumors at radical prostatectomy." (PMID 31366128, 2019). "ERF loss in prostate cells recapitulates the biologic effects induced by ERG gain: activation of androgen-dependent gene expression and induction of tumor formation in cooperation with PTEN loss." (PMID 31366128, 2019). "These include regulation of SOX9 expression by ERG, which is found in tumours with TMPRSS2:ERG fusions, and loss of Zbtb7a, which encodes a factor proposed to antagonize SOX9 function rather than expression." (PMID 29484136, 2018). "Proposed oncogenic mechanisms to achieve increased SOX9 include transcriptional activation by ERG, which is highly expressed in tumours with TMPRSS2:ERG fusions, and loss of Zbtb7a, encoding a protein that antagonizes SOX9 activity." (PMID 29484136, 2018).
tumor (continued). "Loss of pTEN in the cohort was only associated with shorter progression-free survival only in ERG expressing patients, indicating the association between the two transcription factors and tumor progression." (PMID 29562686, 2018). "These associations between GGH expression and tumor clinical characteristics were weaker in the subset of ERG-positive cancers." (PMID 28146062, 2017). "The “triple hit” phenotype (ERG positive/SLC45A3 loss/PTEN loss) was statistically associated with tumor foci containing pattern 3 areas as well." (PMID 29088771, 2017). "High GGH expression was linked to the TMPRSS2:ERG-fusion positive subset of cancers (p < 0.0001), advanced pathological tumor stage, and high Gleason grade (p < 0.0001 each)." (PMID 28146062, 2017). "Remarkably, ERG is the most frequently overexpressed oncogene in PCa, and high expression of ERG is associated with advanced tumour stage, high Gleason score, metastasis and shorter survival times." (PMID 28982366, 2017). "Remarkably, eQTL analysis stratified by fusion type demonstrated a positive correlation between SOX9 gene expression and the rs1859962 risk allele in TMPRSS2:ERG positive tumor tissue." (PMID 27798103, 2016). "Regardless of the CTC isolation technique, multiple rearrangement patterns were observed in ERG-rearranged CTCs, associated with gain of wild-type ERG copies far more prevalent than in the tumor samples including metastatic sites." (PMID 27391263, 2016). "Our findings implicate miR-449a as a tumor suppressor in ERG-associated CaP cells by suppression of SIRT1." (PMID 26988912, 2016). "Statistical associations of 18q deletions and tumor phenotype were weaker in the subsets of ERG-positive and ERG-negative cancers, or vanished completely." (PMID 27861151, 2016). "TMPRSS2:ERG score was positively associated with direct markers of tumor volume, including number of positive cores and maximum percentage of positive cores, in both the academic biopsy cohort and the community biopsy cohort." (PMID 26339615, 2015). "HOXB13 immunostaining was linked to advanced pathological tumor stage, high Gleason grade, and lymph node metastasis (p < 0.0001 each) in subsets of both ERG-negative and ERG-positive cancers." (PMID 25825985, 2015). "Expression of ERG was also associated with clinical markers such as advanced tumor stage, high Gleason score, presence of metastasis and prognostic tumor cell markers such as high Ki67, pEGFR and pAkt." (PMID 24505269, 2014). "Usage of this ATG can be preferentially down-regulated by directed antisense-based compounds, possibly representing the basis of a targeted approach that distinguishes between tumor–associated and normal ERG." (PMID 23472063, 2013). "Their data showed that PTEN deletion was strongly associated with ERG fusion-positive tumors (29.1 versus 10.7%), suggesting a selective advantage for tumor cells harboring both PTEN deletion and ERG fusion." (PMID 24062990, 2013). "Gleason grades of these tumours demonstrate that in 21% of the normal ERG/ETV1 and PTEN loss tumours, Gleason grade was <7 supporting a reclassification of this low Gleason grade patient subgroup." (PMID 20104229, 2010). "There was a significant association between PTEN score and ERG/ETV1 status (P<0.001) with 66% of PTEN loss tumours also having an ERG/ETV1 gene rearrangement compared with 34% of normal PTEN tumours." (PMID 20104229, 2010). "Our findings suggest that ERG may be more closely associated with tumor stage than with recurrence risk." (PMID 40863209, 2025). "Moreover, we showed in a model of human HGF knock‐in mice that the pro‐tumour property of ETV1/ERG factors is closely linked to MET activity and proposed a specific molecular signature of this cooperation after conducting a large‐scale transcriptomic analysis." (PMID 39374163, 2025).
tumor (continued). "While tumour molecular subtyping presents a potential approach for stratifying patients and guiding personalised therapy, the intricacy of the disease complicates the accurate assessment of critical genetic alterations, such as ERG fusions and PTEN variants." (PMID 40165885, 2025). "Here, we show, using cell models of advanced prostate cancer, that ETS translocation variant 1 (ETV1) and transcriptional regulator ERG (ERG) transcription factors (members of the ETS family) promote tumour properties, and that activation of MET signalling enhances these effects." (PMID 39374163, 2025). "Remarkably, treatment with the USP9X inhibitor WP1130 was sufficient to achieve ERG degradation both in vivo and in vitro, thus decreasing the expression of genes associated with ERG, resulting in the inhibition of ERG-positive tumor growth in mouse xenografts." (PMID 40427154, 2025). "For example, tumours with ERG rearrangements or loss of PTEN may demonstrate different therapeutic sensitivities and resistance mechanisms necessitating tailored treatment strategies." (PMID 40165885, 2025). "The combined effect of SETD2 overexpression with ERG gain or PTEN loss may lead to more aggressive tumor behavior, including increased metastatic potential and resistance to treatment, resulting in poorer prognostic outcomes for patients." (PMID 38611113, 2024). "Interestingly, we noticed ERG-positive spheroid-associated tumor cells, which is an unexpected finding." (PMID 37830603, 2023). "Importantly, RAS/RTK mutations in hyperdiploid tumours were typically clonal, whereas in ERG-deleted ALL mutations were almost exclusively subclonal, suggesting the efficacy of RAS/RTK inhibitors will differ between subtypes." (PMID 34753926, 2021). "We are therefore working to add AMACR and p63 to our flow cytometry panel and are also planning to include global genomic and transcriptomic analyses of our PDCOs to evaluate for tumor-specific molecular alterations such as ERG, AR splice-variants, and NEPC markers." (PMID 34581895, 2021). "In the EMMAX corrected dataset rs6698333, an intron variant of Kruppel-like factor 17 (KLF17) and two SNPs (rs1889877, rs3798999) in the intron of adhesion G protein-coupled receptor B3 (ADGRB3) were significantly (< 10-5) associated with ERG fusion status of the index tumor." (PMID 32341752, 2020). "Moreover, the co-culturing of BMSC-EXOsi-PVT1 and ERG-overexpressing MNNG/HOS cells (MNNG/HOSAd-ERG) restored the defect of tumor malignancy caused by the co-culturing of BMSC-EXOsi-PVT1 and MNNG/HOS cells." (PMID 31699956, 2019). "Given that inflammation is a well-known pro-tumor factor, ECs that have undergone EndMT mediated by ERG/FLI1 loss may promote tumor progression in an inflammation-dependent manner." (PMID 30500808, 2018). "Experimental studies have shown that tumor somatic PTEN loss in combination with the TMPRSS2:ERG gene fusion may result in accelerated tumor progression." (PMID 29137428, 2017). "To test whether the over-expression was due to TMPRSS2:ERG fusions, we conducted allele-specific RT-PCR for 49 paired tumor-normal tissue samples." (PMID 28027300, 2016). "Previous studies from our laboratory showed that a high Type I/Type II ratio of ERG gene transcripts correlated with poor prognosis, and a low ratio was associated with favorable clinical-pathologic data based on RT-PCR using tumor cells." (PMID 28191285, 2016). "Expression levels of target genes could provide useful insights into how germline risk variants exert their effects, in particular in tumor subtypes according to TMPRSS2:ERG fusion status." (PMID 27798103, 2016). "In addition, ERG expression was also associated with tumor epithelial cell markers such as high cell proliferation (Ki67), pAKT and pEGFR expression, all known to be related to poor outcome." (PMID 24505269, 2014).